TNF (tumor necrosis factor)
Diseases named in the same sentence as TNF in open-access papers (continued):
Sharing a sentence is not in itself a finding about the gene and the disease.
Flavivirus Infections (13 papers, 2015 to 2025). Infections with viruses of the genus FLAVIVIRUS, family FLAVIVIRIDAE. "Both species exhibited a balanced immune response, with TNF-α and IL-1β playing key roles in inflammation, while IL-10 and IL-13 were prominent in immunomodulation—patterns that are consistent with other flavivirus infections." (PMID 40143314, 2025). "IL-10 acts as an antagonist of TNFα-induced inflammation in a model of peripheral Flavivirus infection." (PMID 40003967, 2025). "Previous studies observed a protective role of TNF-α during other flavivirus infections including West Nile virus and DENV40,41." (PMID 35027643, 2022). "Our results showing IFN-β and TNF following certain Flavivirus infections, are in accordance with previously published works indicating that hMoDC produce both TNF and IFN type I secretion during the infection by DENV or JEV." (PMID 30746342, 2019). "Following flavivirus infection activated glial cells release TNF, IL1β, IL6, and RANTES, all of which promote bystander damage to neurons." (PMID 28873445, 2017). "It has been proposed that the peripheral type I IFN-dependent immune response may protect BBB integrity in an analogous manner, providing the early control of the Flavivirus infection and thus preventing an excessive TNFα-related inflammation." (PMID 40003967, 2025). "Human CD4+ T cell responses to flavivirus infection display a Th1 cytokine pattern, characterized by expression of interferon gamma (IFN-γ), interleukin-2 (IL-2) and tumor necrosis factor alpha (TNF-α)." (PMID 26465323, 2015). "Kupffer cells are fundamental to the pathogenesis of YFV and other flavivirus infections, since the deleterious effects of YFV and the antiviral response are dependent on M1 macrophages and the cytokines that activate these cells, such as TNF-α, IFN-α, and IFN-γ." (PMID 36851765, 2023). "For overproduction of pro-inflammatory cytokines such as ILs, TNF-α, IFN-γ and TGF-β is known to occur in severe DENV, WNV and YFV leading to cytokine storm and vasculopathy, hemorrhage, tissue damage and septic shock characteristic of severe flavivirus infections." (PMID 29990356, 2018).
Gaucher disease (13 papers, 2011 to 2025). Gaucher disease (GD) is a lysosomal storage disorder encompassing three main forms (types 1, 2 and 3), a fetal form and a variant with cardiac involvement (Gaucher disease - ophthalmoplegia - cardiovascular calcification or Gaucher-like disease). "In a previous study, we demonstrated that TNF-alpha levels and P-p38 are sensitive markers of inflammation and cellular stress in Gaucher disease, showing alterations even in the presymptomatic phase." (PMID 40567527, 2025). "Recent studies using induced pluripotent stem cell (iPSC)-derived mφs and lymph nodes from patients with type 2 and type 3 Gaucher diseases have demonstrated that the C5a-C5aR1 axis triggers the induction of TNFα and TGFβ signaling." (PMID 37189685, 2023). "In mouse Gaucher’s disease cells, p38 activation and IL-6 formation by TNF-α treatment were enhanced as compared to those of wild type." (PMID 26312487, 2015). "TNFα production has been suggested as a response to glucosylceramide accumulation in Gaucher disease patients." (PMID 21223590, 2011). "The finding here that TNFα protein was up regulated implicates its downstream cytokine network during Gaucher disease progression." (PMID 21223590, 2011). "Alternatively, or additionally, resistance in vivo could be an indirect consequence of GBA deficiency, attributable to induction of microbicidal lysosomal enzymes (e.g., lysozyme) and cytokines (e.g., tumor necrosis factor) characteristic of Gaucher disease." (PMID 36745788, 2023). "Importantly, in vivo treatment with a pharmacological chaperon, isofagomine, known to enhance GBA1 function in Gaucher’s disease fibroblasts, suppressed the increased p38 activation and TNF-α formation in brain tissues, and extended life span." (PMID 26312487, 2015). "Indeed, some Gaucher disease patients had increased levels of pro-inflammatory (i.e., TNFα, IL-6, IL-8, and IL-1β) and anti-inflammatory cytokines (i.e., CD14) in serum and/or tissues." (PMID 21223590, 2011). "Elevated levels of proinflammatory cytokines such as IL-1, TNF-α, MCP-1, and MIP-1α have been found in the CNS of MPS murine models as well as in the mouse models of Gaucher disease and Krabbe." (PMID 32111039, 2020). "Importantly, Gaucher’s disease patients have been reported to display elevated serum concentrations of hematopoietic growth factors and proinflammatory cytokines, including monocyte/macrophage colony-stimulating factor, TNF-α, interleukin (IL)-1β, IL-8, and IL-6." (PMID 26312487, 2015). "In a model of human Gaucher disease using conduritol B epoxide (CBE)-induced GCase-targeted Mφs stimulated with GC-ICs, there was an increase in the production of pro-inflammatory cytokines, including IFNγ, TNFα, IL1β, IL6, IL12, IL17, IL21, and IL23." (PMID 37189685, 2023). "Neuronopathic Gaucher’s disease mouse model (GBA1V394L/V394L, saposin C-/-) has been also generated, displaying shortened life span and brain proinflammation involving elevations in active p38, IL-6 and TNF-α mRNAs." (PMID 26312487, 2015). "Among them, IL-6 and TNF-α can give rise to mature osteoclasts in the absence of RANKL and have been shown to be upregulated in Gaucher disease models." (PMID 28098793, 2017).
Gliosis (13 papers, 2018 to 2024). Gliosis is the focal proliferation of glial cells in the central nervous system. "Increased number and size of the female brain immune cells was also detected in an obese model induced by Olanzepine, with the gliosis associated with higher levels of TNF-α within the hypothalamus." (PMID 39302596, 2024). "Upregulation of Tenascin C has also been linked to growth factors and cytokines such as TGFβ1, interleukin 1 and TNFα, which have been associated with retinal degenerative disorders, suggesting that Tenascin C may contribute to gliosis." (PMID 30176221, 2018). "In an experimental allergic encephalomyelitis model in rats, co-administration of bee venom and vit B12 reduced TNF-α level, gliosis, and NO generation." (PMID 35949307, 2022). "Inflammatory cytokines that include IL-1, TNF-α, and IL-6 can result in gliosis, as demonstrated in the brain biopsy of seven FIRES cases." (PMID 35663267, 2022). "Gliosis plays an important role in the release of pro-inflammatory cytokines, such as IL-1β and tumor necrosis factor (TNF)-α and is a prominent feature of neurodegenerative conditions." (PMID 33430188, 2021). "Gliosis following Aβ plaque stimulation releases a variety of pro-inflammatory cytokines, including IL-1β, IL-6, and TNF-α, resulting in a persistent inflammatory response." (PMID 34439569, 2021). "YODA1 also caused gliosis, but MG number increased only when combined with HBEGF or TNF." (PMID 36261438, 2022).
glomerular disease (13 papers, 2013 to 2024). "Tumor necrosis factor α (TNFα) promotes inflammation and tissue-destruction in a number of inflammatory diseases, including glomerulopathies." (PMID 32992926, 2020). "Kacprzyk reported elevated serum TNFα in various glomerulopathies including FSGS, but the number of tested patients was low." (PMID 31095586, 2019). "TNF-α induces glomerular disease inrabbits and reduces the GFR in theIPK model." (PMID 38808074, 2024). "During glomerular disease, Twist1 in podocytes limited CCL2-induced recruitment of monocytes/macrophages into the glomerulus and thereby mitigated damage driven by TNF-α–elaborating proinflammatory macrophages." (PMID 34369383, 2021). "Myeloid cells, rather than podocytes, further promoted podocyte injury and glomerular disease by secreting TNF-α." (PMID 34369383, 2021). "Because deletion of TNF-α in podocytes did not impact podocyte injury in the current studies, we conclude that TNF-α produced by proinflammatory macrophages, rather than podocytes, plays a fundamental role in driving glomerular disease." (PMID 34369383, 2021). "A subset of patients with glomerular diseases, including FSGS, may have elevated serum levels of TNFα." (PMID 31095586, 2019). "Antibody-mediated depletion of TNF-α, IL-6, and IL-4Rα after common cold model induction in BALB/cJ mice resulted in a significant decline in albuminuria, suggesting potential therapeutic avenues for treating relapse of primary glomerular diseases after a common cold." (PMID 37040185, 2023).
hyperhomocysteinemia (13 papers, 2010 to 2024). A serious metabolic condition caused by mutations in the MTHFR gene, medications, or nutritional deficiency. "We hypothesize that the high fat diet (HFD) causes dysbiosis, systemic inflammation, and hyperhomocysteinemia (HHcy) in susceptible individuals, which subsequently elevate inflammatory cytokines such as IL-1β, IL-6, IL-17, and tumor necrosis factor alpha (TNF-α)." (PMID 32973741, 2020). "The proposed mechanisms for this are a major systemic inflammatory state involving T cell lymphocytes, tumor necrosis factor alpha (TNF alpha), high density lipoprotein dysfunction, and treatment related hyperhomocysteinemia." (PMID 24368945, 2013). "After 12 months of anti-TNFα treatment, modified TBS was significantly correlated (p < 0.0001) with hyperhomocysteinemia." (PMID 38672734, 2024). "Several studies have also shown that proinflammatory cytokines, such as tumor necrosis factor-alpha (TNF-α) and interleukin-1β (IL-1β), are increased in endothelial cells, retinal cells, and microglia by hyperhomocysteinemia." (PMID 35832851, 2022). "The hyperhomocysteinemia not only induced the secretion of Il-1β, Il-6, RANTES by monocytes, but also promoted inflammation via the TNFα induction, and subsequent MEF2 and NF-κB transactivation." (PMID 34771080, 2021). "Moreover, hyperhomocysteinemia may promote inflammatory processes via oxidative stress, by increased levels of cell adhesion molecules, cytokines (interleukin 6 and tumor necrosis factor-α) and chemokines (high-sensitivity C-reactive protein), which may contribute to the biology of cancer." (PMID 25985325, 2015). "However, hyperhomocysteinemia is positively correlated with increase Hs-CRP and TNF-alpha in the Black SS group compared to the White SS group (r = +0.72, p < 0.001; r = +0.61, p < 0.001, respectively)." (PMID 35684085, 2022).
medulloblastoma (13 papers, 2011 to 2025). A malignant, invasive embryonal neoplasm arising from the cerebellum. "As such, we propose that in response to ZIKV-induced secretion of either TNF-alpha or GM-CSF, these medulloblastoma TAMs would adopt a pro-inflammatory and anti-tumoural phenotype." (PMID 40240536, 2025). "Subsequent studies in rodent L6 myoblasts and human medulloblastoma D283MED-TrkA (MB-TrkA) cells revealed that STK25 undergoes autophosphorylation in response to TNF-α and nerve growth factor (NGF), respectively." (PMID 40639948, 2025). "Here, we observe high TNF-alpha and GM-CSF receptor expression and significant enrichment of their respective pathways in medulloblastoma TAMs." (PMID 40240536, 2025). "Contrasting studies report TNF-alpha as anti-tumoural (cytotoxic or cytostatic) or pro-tumoural for medulloblastoma, and that both TNF-alpha transgene and TNFR antagonist treatment portray favourable outcomes in xenograft models." (PMID 40240536, 2025). "In this study, we investigated the efficacy of targeted systemic delivery of TNFα for the treatment of medulloblastoma by using a tumor‐selective RGD4C.TPA‐mediated TNFα gene delivery platform." (PMID 37331004, 2023). "The use of TNFα in this study as a therapeutic gene showed efficient antitumor activity against medulloblastoma both in vitro and in vivo upon intravenous administration." (PMID 37331004, 2023). "Combination with the chemotherapeutic drug cisplatin used clinically against medulloblastoma resulted in augmented effect through the enhancement of TNFα gene expression." (PMID 37331004, 2023). "Systemic administration of RGD4C.TPA.TNFα to mice‐bearing subcutaneous medulloblastoma xenografts resulted in selective tumor homing of these particles and consequently, targeted tumor expression of TNFα, apoptosis, and destruction of the tumor vasculature." (PMID 37331004, 2023). "Together these findings support systemic tumor targeting by the RGD4C.TPA vector and its efficacy for selective TNFα gene delivery to medulloblastoma." (PMID 37331004, 2023). "Recently, we designed a tumor‐targeted transmorphic phage/AAV (RGD4C.TPA) gene delivery system that we propose to apply for targeted TNFα therapy against pediatric medulloblastoma." (PMID 37331004, 2023). "Next, we evaluated the therapeutic efficacy of systemic delivery of RGD4C.TPA.TNFα against medulloblastoma in mice." (PMID 37331004, 2023). "After confirming the functionality of RGD4C.TPA delivery system using a reporter gene and its selectivity for the αvβ3 and αvβ5 integrins, we constructed vectors carrying a TNFα sequence as a therapeutic gene for medulloblastoma." (PMID 37331004, 2023). "We investigated the efficacy of RGD4C.TPA.TNFα in vitro using human medulloblastoma cell lines, and in vivo in tumor‐bearing mice." (PMID 37331004, 2023). "Next, we investigated the viability of medulloblastoma tumor cells following TPA transduction to assess the antitumor effect of RGD4C.TPA.TNFα." (PMID 37331004, 2023). "This study describes the efficacy of a transmorphic phage (TPA)‐guided TNFα gene delivery for the treatment of pediatric medulloblastoma." (PMID 37331004, 2023). "In vitro RGD4C.TPA.TNFα treatment of human medulloblastoma cells generated efficient and selective TNFα expression, subsequently triggering cell death." (PMID 37331004, 2023). "Additionally, we identify TNF-alpha as a marker of poor prognosis in medulloblastoma, likely in part due to enhanced tumour growth." (PMID 40240536, 2025). "Our in silico analysis indicates that all medulloblastoma TME immune cells are primed to respond to TNF-alpha paracrine signalling and that TNF-alpha endocrine signalling would polarise myeloid cells to upregulate pro-survival and innate immune recognition genes." (PMID 40240536, 2025).
medulloblastoma (continued). "Performing a five-year survival analysis on clinical and gene expression data for 375 medulloblastoma patients, we observe high TNF-alpha expression to be significantly correlated with worse survival and high TNFRSF9 expression to be significantly correlated with improved survival." (PMID 40240536, 2025). "Therefore, we sought to test the effects of combining CDDP with RGD4C.TPA.TNFα particle, as this chemotherapeutic agent has been used clinically to treat medulloblastoma patients." (PMID 37331004, 2023). "Thus, our RGD4C.TPA.TNFα particle provides selective and efficient systemic delivery of TNFα to medulloblastoma, yielding a potential TNFα anti‐medulloblastoma therapy while sparing healthy tissues from the systemic toxicity of this cytokine." (PMID 37331004, 2023). "In this study, we used the recently reported TPA particles characterized by enhanced gene expression, high titer production, and large DNA sequence accommodation, then constructed the RGD4C.TPA.TNFα to evaluate the efficacy of guided systemic delivery of TNFα gene for medulloblastoma treatment." (PMID 37331004, 2023). "Next, to check whether the tumor homing of RGD4C.TPA.TNFα translates into selective expression of TNFα in medulloblastoma, tumor‐bearing mice were intravenously injected with targeted or nontargeted TPA.TNFα twice at 3 days intervals." (PMID 37331004, 2023). "Thus, we used a recently designed tumor‐targeted bacteriophage (phage)‐derived particle, named transmorphic phage/AAV, TPA, to deliver a transgene expressing the tumor necrosis factor‐alpha (TNFα) for targeted systemic therapy of medulloblastoma." (PMID 37331004, 2023). "The in vitro 3D brain organoid models co-cultured with embryonal CNS tumor cells also showed ZIKVBR tropism to the tumor cells and an immune response mediated by TNF signaling, an important pathway that enhances the sensitivity of tumors to immunotherapy, including medulloblastoma." (PMID 34696533, 2021). "Studies have observed the cytotoxic effects of TNF-alpha on medulloblastoma." (PMID 22536907, 2012). "In medulloblastoma tumors, the crosstalk between C3a and C3RA1, which is expressed by infiltrating astrocytes and microglia, causes the release of Tumor necrosis factor alpha (TNF-α), and TNF-α stimulates chemokine ligand 5 (CCL5) release in glia and macrophages." (PMID 36834607, 2023). "Here, we observe recombinant TNF-alpha as pro-tumoural rather than cytotoxic to medulloblastoma and ATRT cells under normal conditions." (PMID 40240536, 2025). "All immune cells express receptors for TNF-alpha (TNFRSF1A and TNFRSF1B) and IFN alpha (IFNAR1 and IFNAR2) and are enriched for these pathways, indicating that all these immune cell types are primed to respond to secreted TNF-alpha and IFN alpha in the medulloblastoma TME." (PMID 40240536, 2025). "Therefore, based on the superiority of the CMV promoter in human medulloblastoma cells and its significant activation by CDDP, as compared to the GRP78 promoter, we selected CMV‐guided TNFα expression as the sequence to use in successive in vivo investigation of RGD4C.TPA." (PMID 37331004, 2023).